DNMT1 (DNA methyltransferase 1)
Diseases named in the same sentence as DNMT1 in open-access papers (continued):
Sharing a sentence is not in itself a finding about the gene and the disease.
cancer (continued). "Our data supports a model in which UHRF1-dependent H3 ubiquitination ‘bookmarks’ genomic regions of low CpG density in late replicating chromatin for re-methylation by DNMT1, and that a disrupted UHRF1-DNMT1 ubiquitin signaling axis contributes to DNA hypomethylation in cancer." (PMID 39607687, 2024). "TQ also decreased the expression of DNA methyltransferase 1 (DNMT1) in both cancer cell types." (PMID 38257347, 2024). "In addition, G9a/DNMT1 inhibition sensitizes cancer cells to chemotherapy (cisplatin), targeted therapy (trametinib) and epigenetic therapy (vorinostat)." (PMID 39488528, 2024). "In cholangiocarcinoma, miR-152 targeted DNMT1, with reduced expression in cancer cells." (PMID 39606232, 2024). "We then examined the methylation alterations in the PI3K-AKT pathway, and found that while the associated DMSs were slightly hypomethylated in cancer cells compared with those in NOK cells, DNMT1 knockdown resulted in extensive hypomethylation of critical genes." (PMID 38755637, 2024). "Notably, a significant decrease in DNMT1 expression in cancer correlated with a notable reduction in mortality and the hazard ratio for overall survival." (PMID 38755637, 2024). "The expression levels of total and phosphorylated proteins were then assessed, revealing a significant reduction in phosphorylated AKT and mTOR in sh-DNMT1 cancer cells, although the overall protein expression levels of PI3K and AKT did not exhibit substantial alterations." (PMID 38755637, 2024). "By analyzing the expression patterns of these DNA methylation writers and erasers, we observed that the most notable alterations in cancers were elevated levels of DNMT1, DNMT3A, and DNMT3B, which is consistent with the previous result of global DNA hypermethylation in a broad array of cancers." (PMID 38666956, 2024). "The deletion of DNMT1 may have released its repression on the TET2 promoter in the cancer cells and prime these cells for TET2 upregulation upon exposure to DNMTi." (PMID 39057134, 2024). "Moreover, c-Jun increases expression and regulates function of the DNA methyltransferase-1 (DNMT1) in cancer cells." (PMID 38177097, 2024). "Additionally, we found the expression of DNA methyltransferase 1 (DNMT1) was increased in cancer specimens in three datasets." (PMID 36824133, 2023). "Additionally, we examined the correlation between DNMT1 and other immune checkpoints (ICs) across various types of cancer." (PMID 37628671, 2023). "Thus, DNMT1 deletion confers resistance to DNMTi, and their anti-cancer activity is determined by DNA damage effects." (PMID 37045940, 2023). "Epigenetic drugs like DNA methylatrasnferase-1 (DNMT1) inhibitors have been shown to have positive effects in cancer treatment, but more recent studies demonstrated that DNMT inhibitors also have the potential to improve the effect of immune checkpoint blockade therapy by modulating the TIME." (PMID 37835379, 2023). "Our study revealed a positive correlation between Th2_cells and DNMT1 in various cancer types." (PMID 37628671, 2023). "DNMT1 is typically downregulated in differentiated cells/tissues but is re-expressed in multiple cancers where it promotes proliferation and self-renewal; particularly in cancer-initiating cells." (PMID 37055433, 2023). "This strategy is not purely restricted to DNMT1 but conveyable to other epigenetic factors thereby broadening the clinical applications of RNA aptamers to multiple types of cancers or diseases associated with epigenetic alterations." (PMID 36609400, 2023).
cancer (continued). "In addition, curcumin inhibits DNA methylation in the promoter region of numerous cancer-related genes by lowering the amount of DNA methyltransferase 1 (DNMT1)." (PMID 37371804, 2023). "DNMT1 is highly expressed in cancer, and inhibition of DNMT1 slows the progression of cancer." (PMID 36874006, 2023). "Additionally, we explored the correlation between IL18RAP and five methyltransferases (DNMT3L, DNMT3B, DNMT3A, TRDMT1, and DNMT1) across cancers." (PMID 37698530, 2023). "piR-823 regulates the methylation of cancer stem cells by regulating DNMT1, DNMT3A, and DNMT3B." (PMID 38031146, 2023). "We analyzed frequency of DNMT1 gene deletion in human cancers." (PMID 37045940, 2023). "In addition to some already identified pro-cancer downstream molecules, the activation of mTOR signalling was found to promote DNA methylation by increasing the translation of DNMT1." (PMID 37088830, 2023). "Moreover, studies also revealed that inhibition of DNMT1 expression can attenuate cancer proliferation and motility." (PMID 36273188, 2022). "DNMT1 inhibits tumor suppressor genes in several cancers by hyper-methylating gene promoters." (PMID 35880568, 2022). "SIRT1 may facilitate cancer progression by epigenetically modulating the polycomb repressor complex 4 (PRC4) comprising DNMT1, DNMT3b, polycomb group (PcG) proteins, embryonic ectoderm development isoform 2 (EED2), and enhancer of zeste homolog 2 (EZH2)." (PMID 35054489, 2022). "Studies showed that T-dCyd and aza-T-dCyd could deplete DNMT1 in cancer cells resulting from the re-expression of TSG p15." (PMID 37077808, 2022). "The exact mechanisms behind the aberrant expression of DNMT1 are currently unknown, but studies in other cancers are indicating that the DNMT1 levels could be regulated by miR-148a." (PMID 36059621, 2022). "In addition, FEN1 can modify the epigenetic features in cancer cells by inducing the upregulation of DNA methyltransferase 1 (DNMT1) and DNMT3a and interacting with DNMT3a through proliferating cell nuclear antigen (PCNA)." (PMID 36672839, 2022). "In addition, a close relationship was observed between PLOD2 expression and mutations in 4 methyltransferases (DNMT1, DNMT2, DNMT3A, DNMT3B) in several cancer types." (PMID 35586565, 2022). "GSK3B enhances the stability of DNMT1 and maintains DNA methylation and chromatin structure, which may contribute to the growth of cancer cells, while the mechanism of GSK3B and DNMT1 protein has not been clearly reported in PTOA." (PMID 35747513, 2022). "Many cancers have been shown to have oncogenic DNMT1-mediated DNA methylation." (PMID 35880568, 2022). "DNMT1 is involved in the holding of sequence methylation during cellular proliferation, which is necessary for the faithful maintenance of DNA methylation patterns, as well as abnormal silencing of TSGs in cancer cells." (PMID 36091786, 2022). "By blocking acetylated STAT3 dimerization and DNMT1 interaction SHF may serve as an attractive therapeutic target for patients with a range of cancers, not only GBM." (PMID 35843865, 2022). "NNMT overexpression and DNMT1 inhibition render OXPHOS inhibition‐sensitive cancer cells resistant." (PMID 36382559, 2022). "DepMap categorizes DNMT1 as a common essential gene (a gene that ranks within the topmost depleting genes in at least 90% of cancer cell lines tested) based on the gene effects observed across a large number of cell lines screened using the shRNA and CRISPR libraries." (PMID 36329185, 2022). "Indeed, the SRA (SET and RING-associated) domain of UHRF1 recognizes hemi-methylated DNA generated during DNA replication which allow UHRF1 to recruit DNMT1 in order to methylate the newly synthesized DNA strand, resulting in silencing of many TSGs in cancer." (PMID 35566130, 2022). "Thus, the status of NNMT and DNMT1 in cancer cells provides an excellent base for developing biomarkers for selecting cancer patients suitable for therapies targeting the mitochondrial OXPHOS pathway." (PMID 36382559, 2022).
cancer (continued). "Interpreting the mechanism of EZH2 and DNMT1 conductor in cancer immunity throws light on the promising benefit of the combinational treatment of epigenetic-modifying drugs (such as EZH2 or DNMT1 inhibitor) and immunotherapy (such as TAMs modulator) in patients with cancer." (PMID 36038549, 2022). "It has been reported that the loss of DNMT1 results in global and gene-specific demethylation and re-expression of tumour-suppressor genes in human cancer cells, which demonstrates that DNMT1 is necessary to maintain global methylation and aberrant CpG island methylation in human cancer cells." (PMID 35838271, 2022). "Studies have shown that DNMT1 is highly expressed in many cancers." (PMID 36273188, 2022). "Indeed, patients with tumors expressing high level of DNMT1 in stromal fibroblasts or cancer cells had significantly poorer OS rates." (PMID 35719957, 2022). "Although it seems that expressions of DNMT1, UHRF1, and DNMT3A are also upregulated in OXPHOS inhibition‐sensitive cancer cells identified in our screen, only DNMT1 expression exhibits a significantly positive correlation with cancer cell sensitivity to OXPHOS inhibition." (PMID 36382559, 2022). "Furthermore, we identified pan-cancer replicated associations of APEX1, RECQL, and DNMT1 with dHRICA (with DNMT1 additionally associating with dHRVAE2)." (PMID 35764656, 2022). "Also, highly abnormal methylation patterns can arise through pharmacological DNMT1 inhibition or alteration of the methylation machinery, as observed in cancer." (PMID 36354000, 2022). "Dnmt1 is essential for mammary and cancer stem cell maintenance and tumorigenesis." (PMID 36329185, 2022). "It was reported that DNMT1-mediated DNA methylation regulated p21 expression in cancer cells." (PMID 35880568, 2022). "Interestingly, treatment of these OXPHOS inhibitors (Gboxin, Oligomycin A, and Berberine) decreases DNMT1 expression in OXPHOS inhibition‐sensitive cancer cells, implying a reciprocal regulation between mitochondrial metabolism and epigenetic regulation." (PMID 36382559, 2022). "After a systematic analysis of OXPHOS sensitive and resistant cancer cell lines, we revealed that SAM‐regulated enzyme NNMT and SAM‐consuming DNA methyltransferase DNMT1 negatively and positively correlated with cancer cell sensitivity to OXPHOS inhibition, respectively." (PMID 36382559, 2022). "Many cancers have overexpression or increased activity of DNMT1, DNMT3a and/or DNMT3b." (PMID 35747820, 2022). "Thereby, DNMT1 level in both cancer cells and their adjacent stromal fibroblasts could constitute a powerful prognostic biomarker for these high-risk patients who need downstaging tumors to facilitate breast conservation therapy." (PMID 35719957, 2022). "The role of DNMT1 in tumorigenesis has been well-studied across several cancer lineages." (PMID 36329185, 2022). "Therefore, researchers have been pushing to investigate the mechanism of DNMT1 in cancer, aiming to improve the effectiveness of comprehensive treatment." (PMID 36091786, 2022). "The reduction in DNMT1 activity by inhibiting GSK3β-mediated phosphorylation of DNMT1 resulted in the re-expression of hormone receptors AR and ER in PCa and BCa cells, respectively, and re-sensitized these cancers to antihormones." (PMID 35402240, 2022). "Therefore, the development of more potent DNMT1 inhibitors acquiring potential binding pocket features is highly desirable to restore the suppressed TSGs (RUNX3) in cancer therapeutics." (PMID 35898303, 2022). "However, our results also show that NNMT inhibition and DNMT1 overexpression cannot render OXPHOS‐resistant cancer cells sensitive." (PMID 36382559, 2022). "In addition, the hyperexpression of DNMT1 in GC tissues was greatly correlated to reduced E-cadherin expression, which indicated that an increase in the DNMT1 expression level would elevate the migration ability of the cancer cells." (PMID 36091786, 2022).
cancer (continued). "Pan-cancer analysis also showed upregulation of DNMT1 transcription in several cancer types." (PMID 33500531, 2021). "DNMT1 is the main DNA methylating enzyme responsible for the maintenance DNA methylation in normal cells, as well as for the maintenance and de novo DNA methylation in cancer cells." (PMID 33498667, 2021). "The natural product compounds such as epigallocatechin-3-gallate (EGCG), catechin, and quercetin exhibit a plausible activity as an inhibitor of DNMT1, resulting in DNA demethylation, which reactivates the tumor suppressor gene expression, thereby reducing the cancer cell growth rate." (PMID 33450856, 2021). "Future pan-cancer studies may lead to better understanding and could help determine whether these findings represent conserved molecular mechanisms controlling DNMT1 protein expression." (PMID 34572918, 2021). "There are two studies in different cancer types showing diverging results for DNMT1." (PMID 34572918, 2021). "TQ-induced upregulation of TSGs in cancer could be attributed in large part to the inhibitory effects of TQ on the UHRF1/DNMT1/HDAC complex, with subsequent apoptosis induction." (PMID 33922029, 2021). "This study showed the feasibility of PDX model to explore the mechanisms of mTOR resistance acquisition and suggested that genetic alterations, including that of DNMT1, which alter the methylation status in cancer cells, are one of the potential mechanisms of developing resistance to temsirolimus." (PMID 33107222, 2021). "DNMT1 activity could be regulated at post-translational level through phosphorylation by a serine/threonine kinase, leading to a global hypomethylation in cancer." (PMID 34944912, 2021). "Whether the ac-DNMT1 protein levels and disease outcomes are context dependent on the cancer type requires further investigation." (PMID 34572918, 2021). "DNA hypermethylation may occur due to enhanced activity of two DNA methyltransferases (DNMT1 and DNMT3b), surrounding bivalent promoters in cancer cell lines." (PMID 33430434, 2021). "Previous research also indicated that DNMT1 was implicated in cell metastasis, such that downregulation or inhibition of DNMT1 could facilitate the metastasis of cancer cells." (PMID 34681726, 2021). "Additionally, DNMT1 expression levels were significantly higher in carcinoma tissues than in adjacent tissues." (PMID 34150611, 2021). "Similarly, the Western blot test showed that DNMT1 protein was significantly higher in carcinoma tissues (n = 5) than in adjacent normal tissues (n = 5)." (PMID 34150611, 2021). "Therefore, we investigated the effect of mutations on DNA methylation modification genes such as DNMT1, DNMT3A, MBD1, MBD4, TET1, TET2 and TET3 through a pan-cancer analysis." (PMID 32093698, 2020). "Among DNMT1, DNMT3A and DNMT3B, mutations in DNMT3A have been reported most frequently in cancer." (PMID 32751889, 2020). "Also, caffeic acid, an active constituent of CAPE was shown to inhibit DNMT1 and demethylated RA receptor β in cancer cells." (PMID 33244299, 2020). "A prominent example of this hypothesis has been suggested for the polyphenol compound from green tea, EGCG, which has been proposed to inhibit DNMT1 and reactivate methylation-silenced genes in cancer." (PMID 33375520, 2020). "Interestingly, especially in the context of highly methylated BRAF mutant cancers, the loss of MEN1 has been associated with aberrant DNMT1 activity and an altered DNA methylation landscape." (PMID 32384699, 2020). "The most common epigenetic change in cancers is hypermethylation of the CpG islands within the promoters of tumor suppressor genes due to either increased activity or overexpression of DNA-methyltransferase 1 (DNMT1)." (PMID 33273553, 2020). "Similarly, a new quinoline-based molecule, MC3353, can also inhibit the activity of DNMT1 and DNMT3A to reverse hypermethylation caused by cancer." (PMID 32751889, 2020).
cancer (continued). "In addition, MUC1 regulates DNA methylation by upregulating the expression of DNMT1 and DNMT3b methyltransferases in human carcinoma cells." (PMID 33060563, 2020). "Notably, our co-expression analysis by database mining provides clear evidence for a widespread co-expression of UHRF1 and DNMT1 in normal tissues and numerous cancer cells." (PMID 30696879, 2019). "Nevertheless, it has also been suggested that impaired interaction between UHRF1 and DNMT1 could be the origin of the global hypomethylation in cancer cells." (PMID 31249594, 2019). "Since UHRF1 and DNMT1 are co-expressed in different tissues and cancer cells and they are regulated at the transcription level by the MEK/ERK pathway, we hypothesized that they are co-regulated by a set of common transcription factors." (PMID 30696879, 2019). "Similarly, 2i treatment also induced a broad reduction of DNMT1 mRNA in most cancer cell lines, with exception of KYSE140 and KYSE450." (PMID 30696879, 2019). "Moreover, resveratrol displayed a cancer preventative role by recruiting DNMT1 to the BRCA1 promoter and enhancing MCF-7 breast cancer cell silencing." (PMID 31505792, 2019). "Moreover, because the inhibition of UHRF1 leads to DNA demethylation by suppressing the recruitment of DNMT1 to newly synthesized hemi-methylated DNA, substantial numbers of cancer cells retain hemi-methylated DNA after UHRF1 depletion." (PMID 31064417, 2019). "As DNMT1 plays an important role in mediating the methylation of microRNAs in cancer cells, we investigated whether it was involved in the regulation of hsa-miR-124-3p / BCAT1 in ESCC." (PMID 31226958, 2019). "Data mining reveals a marked co-expression of UHRF1 and DNMT1 in normal tissues as well as cancers." (PMID 30696879, 2019). "Thus, the activated MEK/ERK pathway is required for elevated expression of UHRF1 and DNMT1 in these cancer cell lines." (PMID 30696879, 2019). "We picked DNMT1 to test this hypothesis as it is a major hub in the DU‐SR network and a key cancer gene in non‐small‐cell lung cancers (NSCLCs)." (PMID 30858180, 2019). "We showed that 2i also regulates UHRF1/DNMT1 expression in cancer cells." (PMID 30696879, 2019). "The DNMT1 was significantly associated with patient survival times only in one cancer type (not shown), and it was seen that the DNMT3A expression did not affect patient survival." (PMID 31828117, 2019). "DNA methyltransferase 1 (DNMT1), the most abundant DNA methyltransferase in humans, is primarily responsible for maintenance of the DNA methylation pattern and is considered an important cancer drug target." (PMID 31306451, 2019). "Thus, inhibition of either MEK1/2 or ERK1/2 down-regulated UHRF1 and DNMT1 expression in these cancer cells." (PMID 30696879, 2019). "DNMT1 is also indispensable for mammary and cancer stem cell maintenance and tumorigenesis." (PMID 29416775, 2018). "Moreover, psammaplin A has been previously shown to inhibit DNMT1, the enzyme responsible of DNA methylation maintenance during replication, and to induce cancer cell death." (PMID 30572618, 2018). "Moreover, tumor suppressor gene Rb1 promoter became hypermethylated due to DNMT1 overexpression in several human cancers." (PMID 30680063, 2018). "Interestingly, DNMT1 plays a role in the self-renewal of cancer stem cells, which are involved in both tumorigenesis and tumor metastasis." (PMID 29954131, 2018). "In the outlier control samples, we identified proteins DNMT1 (DNA Methyltransferase 1), INSR (insulin receptor) and HDAC1 (histone deacetylase 1) displaying a regulation pattern previously associated with different cancer types, including MIBC." (PMID 30419021, 2018). "Furthermore, DNMT1 has de novo activity in human cancer cells and plays also important roles in maintaining genome stability." (PMID 29416775, 2018). "Therefore, multiple studies have evolved in the last decade attempting to develop therapeutic interventions targeting DNMT1 in cancer therapy." (PMID 30190481, 2018).